FNDC3B (fibronectin type III domain containing 3B)
Diseases named in the same sentence as FNDC3B in open-access papers (continued):
Sharing a sentence is not in itself a finding about the gene and the disease.
brain cancer (1 paper, 2023). A primary or metastatic malignant neoplasm affecting the brain. "Notably, the cancer-to-normal ratio of FNDC3B expression within brain cancer exceeded 3.0 (p < 0.0001), significantly higher than the ratios in all other organs, which remained below 1.6." (PMID 38137388, 2023).
brain tumors (1 paper, 2023). "Within brain tumor tissues, we observed that FNDC3B expression levels progressively increased from Grade 2 to Grade 4 (Grade 2, 2.2-fold, p < 0.0001; Grade 3, 2.7-fold, p < 0.0001; Grade 4, 3.6-fold, p < 0.0001)." (PMID 38137388, 2023). "We found that FNDC3B was exceptionally highly expressed in GBM compared to other organ cancers and that the expression levels of FNDC3B increased along with the grade of brain tumors." (PMID 38137388, 2023).
Coagulopathy (1 paper, 2022). "Coagulopathy was reported in GTF2I-RARA, FNDC3B-RARA, NUP98-RARA, and TNRC18-RARA-positive AML." (PMID 35494081, 2022).
esophageal squamous cell carcinoma (1 paper, 2017). Esophageal squamous cell carcinoma (ESCC) is a type of esophageal carcinoma (EC) that can affect any part of the esophagus, but is usually located in the upper or middle third. "Also, the overexpression of miR-34a significantly inhibited the migratory and invasive potential of esophageal squamous cell carcinoma (ESCC) cells via inhibition of FNDC3B (Fibronectin Type III Domain Containing 3B), MMP2 (matrix metalloproteinase-2) and MMP9 expression levels." (PMID 29036883, 2017).
invasive breast carcinoma (1 paper, 2022). A carcinoma that infiltrates the breast parenchyma. "FNDC3B was shown to be overexpressed in invasive breast cancer, which was identified by the Finak dataset, whereas we obtained the opposite conclusion from other databases, including TCGA, Radvanyi, and Gluck." (PMID 36626432, 2022).
ischemic cardiomyopathy (1 paper, 2019). Ischemic cardiomyopathy is a cardiomyopathy in which a weakness in the muscle of the heart due to inadequate oxygen delivery to the myocardium with coronary artery disease being the most common cause. "Interestingly, humans express an ortholog (86% identity) of this circRNA, and we found that expression of the human circFndc3b ortholog was also significantly reduced in the LV tissues of ischemic cardiomyopathy patients compared to non-failing hearts, unlike the linear Fndc3b mRNA." (PMID 31541092, 2019).
mesenchymal tumors (1 paper, 2015). "FNDC3B, FILIP1L and P2RY5 (cluster II) were consistently up-regulated in mesenchymal tumors." (PMID 26295306, 2015).
nasopharyngeal carcinoma (1 paper, 2023). A carcinoma arising from the nasopharyngeal epithelium. "in 2020 identified that the 3′-UTR shortening of fibronectin type III domain containing 3B (FNDC3B) mRNA mediated its overexpression in Nasopharyngeal carcinoma(NPC)and promoted NPC progression by targeting myosin heavy chain 9 (MYH9)." (PMID 36816917, 2023).
oral squamous cell carcinoma (1 paper, 2022). "circRNA_0001971 contributes to oral squamous cell carcinoma progression via sponging miR‐186‐5p to upregulate FNDC3B." (PMID 35060189, 2022).
renal cell carcinoma (1 paper, 2022). "A study reported that overexpression of circ-FNDC3B may weaken the effects of curcumin on inhibiting proliferation and promoting apoptosis of RCC cell through regulating the miR-138-5p/IGF2 axis, which provides a new perspective for the treatment of renal cell carcinoma." (PMID 35223991, 2022).
steatosis (1 paper, 2025). Increased lipid within the cytoplasm of cells. "The 10 most significantly downregulated genes in NAFLD included genes protecting against steatosis (MET) and fibrosis (GAS5), cancer suppression (RBMS1), and genes downregulated in HCC (FNDC3B)." (PMID 40489530, 2025).
viral hepatitis (1 paper, 2016). An acute or chronic inflammation of the liver parenchyma caused by viruses. "Here, our tissue array data showed that FNDC3B was highly expressed in normal liver tissue infected with viral hepatitis (45%, 9/20)." (PMID 27385217, 2016).
Zika virus infection (1 paper, 2016). "The novel interactions of FNDC3B with IFITM3 and SPTA1, ARPC1B and AGTR2 with IFITM1 may shed light on mechanisms of host invasion underlying cytoskeletal re-arrangements that follow Zika virus infection." (PMID 29333229, 2016).
tumor (40 papers, 2013 to 2025). "Recently, an increasing number of studies have elucidated the mechanisms underlying the role of FNDC3B in tumor progression, particularly in tumor invasion and metastasis." (PMID 38581008, 2024). "Additionally, we validated the diagnostic value of FNDC3B in PC using ROC curve analysis which was significantly higher than traditional tumor marker of PC, such as CA19-9 for diagnosis (0.896 vs. 0.83)." (PMID 38581008, 2024). "The comparative analysis of FNDC3B gene expression in different immune subtypes in LGG suggested that FNDC3B may be strongly linked to immunological properties in the tumor microenvironment." (PMID 36275754, 2022). "This interaction leads to a decrease in the abundance of linear FNDC3B mRNA—an oncogene—while promoting the formation of circFNDC3B, which possesses tumor-suppressive properties." (PMID 41019082, 2025). "In vivo metastasis experiments have revealed that the knockdown of FNDC3B reduces tumor nodule formation." (PMID 38403291, 2024). "Growing evidence suggests the significance of FNDC3B in tumorigenesis, particularly in cell migration and tumor metastasis." (PMID 38403291, 2024). "FNDC3B is a typical fibronectin-related protein that plays a vital role in tumor progression by activating downstream signaling pathways." (PMID 38581008, 2024). "The results both confirmed that the expression of FNDC3B was significantly higher than that observed in tumor-adjacent tissue." (PMID 38581008, 2024). "The study demonstrated a significantly higher expression of FNDC3B in tumor tissues compared to normal pancreatic tissues, and this expression was significantly associated with various clinicopathological parameters." (PMID 38581008, 2024). "The findings suggest that FNDC3B plays a crucial role as a tumor promoter in PC progression and holds immense potential as a therapeutic target for PC treatment." (PMID 38581008, 2024). "Western blot analyses further confirmed elevated FNDC3B expression in PC cell lines relative to normal pancreatic ductal epithelial cells, suggesting a potential role for FNDC3B as a tumor promoter in PC." (PMID 38581008, 2024). "In myeloma cells, FNDC3B proteins interact with tumor suppressors FAM46C and p62 proteins and integrate protein and secretory homeostasis." (PMID 38137388, 2023). "Among the neoantigens are well-known genes associated with tumor progression and metastases, such as HAUS3, NSDHL, MAGEA10, FNDC3B, TEAD1, DHX33, PGM5, and MLL2." (PMID 36607962, 2023). "FNDC3B has already been reported to promote tumor progression in various cancers via multiple mechanisms." (PMID 38129874, 2023). "The xenograft assays demonstrated that knockdown of FNDC3B significantly restrained the tumor growth in vivo." (PMID 38129874, 2023). "Abnormal circFNDC3B and FNDC3B mRNA expression were not only correlated with tumor size, Enneking stage and/or lymph node metastasis status, but also associated with the prognosis of OS patients." (PMID 38129874, 2023). "Overall, our study discovered that circRNA_0001971 was a tumor promoter in OSCC progression by targeting miR‐186‐5p/FNDC3B axis." (PMID 35060189, 2022). "FNDC3B expression was positively correlated to the tumor-infiltrating lymphocytes and immune infiltration score, and high FNDC3B expression was accompanied by the increased expression of B7-H3, PD-L1, TIM-3, PD-1, and CTLA-4." (PMID 36275754, 2022). "Mechanistic studies identified a novel regulatory mechanism of LINC00355/miR-1225/FNDC3B axis in carcinogenesis and metastasis, suggesting a novel clue for tumor treatments." (PMID 34603558, 2021). "HBx also promotes tumor metastasis by inducing cyclooxygenase-2 and matrix metalloproteinase-1, 2, 3, and 9 expressions, and repressing E-cadherin and fibronectin type III domain containing 3B (FNDC3B) expressions." (PMID 27409165, 2016). "Immunohistochemical analysis of tumor nodule sections indicated the tumor nodule expressed human FNDC3B." (PMID 27385217, 2016).
tumor (continued). "To further confirm the role of FNDC3B in tumor metastasis, we analyzed the expression of FNDC3B in 15 metastatic and 44 primary HCC tissues by tissue array." (PMID 27385217, 2016). "On the other hand, knockdown of FNDC3B using short-hairpin RNA reduced tumor nodule formation in both intra- and extra-hepatic metastasis." (PMID 27385217, 2016). "Upregulation of miR-143 expression transcribed by NF-kappa B in HBV-HCC promotes cancer cell invasion/migration and tumor metastasis by repression of fibronectin type III domain containing 3B (FNDC3B) expression." (PMID 24672518, 2014). "Advanced study showed that up-regulation of miR-143 expression promotes cancer cell invasion/migration and tumor metastasis by repression of FNDC3B expression." (PMID 24993656, 2014). "Another study also reported that FNDC3B was down-regulated in tumor cells with high metastatic potential." (PMID 25408705, 2014). "As expected, the expression of miR-143 was significantly decreased whereas FNDC3B protein levels were enhanced in the tumor tissue of the group of miR-143-inhibitor." (PMID 23383988, 2013). "FNDC3B is a member of the fibronectin family, which regulates cell motility, and is down-regulated in tumor cells with high metastatic potential." (PMID 23383988, 2013). "We also investigate the expression of miR-143 and FNDC3B in the tumor tissue of nude mice by RT-PCR and western blotting." (PMID 23383988, 2013). "Given the well-established involvement of ECM in tumor progression, it is plausible that FNDC3B may function as a tumor promoter across various malignancies." (PMID 38581008, 2024). "Additionally, several tumor suppressor miRNAs have been shown to inhibit cell migration by targeting FNDC3B." (PMID 38403291, 2024). "To enhance the prognostic efficacy of FNDC3B in PC, we developed a nomogram incorporating radiation therapy, primary therapy outcome, histologic grade, residual tumor status, anatomic neoplasm subdivision along with FNDC3B expression to accurately predict the 1-, 2-, and 3-year OS for PC patients." (PMID 38581008, 2024). "Because FNDC3B functions as an oncogene in many cancers and we also confirmed its malignant role in OS, we think circFNDC3B may exert tumor inhibitory effects by repressing FNDC3B mRNA." (PMID 38129874, 2023). "Indeed, another circular RNA derived from exon 5 and exon 6 of FNDC3B gene, hsa_circ_0006156, has been verified to be a tumor suppressor in malignancies such as colorectal cancer and bladder cancer." (PMID 38129874, 2023). "In addition, we showed that the expression of circFNDC3B decreased while FNDC3B mRNA increased in OS tumor tissues and the expression level of circFNDC3B and FNDC3B mRNA in OS tissues were negatively correlated with each." (PMID 38129874, 2023). "Furthermore, we explored the proportions of 22 types of immune cells for LGG using CIBERSORTx to acquire a deeper understanding of the relationship between FNDC3B expression and tumor immune infiltrates." (PMID 36275754, 2022). "In addition, direct evidence from our knockdown and overexpression experiments indicates that FNDC3B promotes cell migration and tumor metastasis in HCC." (PMID 27385217, 2016). "Considering the dual role of STAT3 as either a pro-oncogene or tumor-suppressor, subject to the genetic background of the tumor, FNDC3B downregulation might induce upregulation of STAT3 phosphorylation and PTEN expression solely in U87MG cells treated with siFNDC3B constructed in this study." (PMID 38137388, 2023). "High level of miR-143 could promote tumor metastasis through FNDC3B in vitro and in vivo." (PMID 31448232, 2019). "We have performed differential mRNA expression analysis of NY-ESO-1, FNDC3B, and MLANA, which are the most common antigens among the tumor-specific groups." (PMID 38488909, 2024). "Of note, we observed that CYTOR‐related nodal genes were mainly involved in EMT, p‐EMT or tumor invasion in HNSCC, including LAMB3, PDPN and FNDC3B." (PMID 38032139, 2024).
tumor (continued). "Mechanistically, circ-FNDC3B-218aa inhibits the expression of Snail and subsequently promotes the tumor-repressive effect of FBP1, which results in the suppression of tumor progression and EMT." (PMID 35223470, 2022). "Overexpression of FNDC3B in HCC cell lines enhanced cell migration and invasion, knockdown of FNDC3B using shRNA reduced tumor nodule formation in intra- and extra-hepatic metastasis." (PMID 32972270, 2020). "Of these seven, six genes—ECT2, NCEH1, TNFSF10, FNDC3B, GHSR, and SEMA6D—have either been observed at elevated expressions in tumor cells or have been documented acting as oncogenes for specific cancers in humans (genes that can transform cells into tumor cells)." (PMID 33767816, 2021). "FNDC3B is one of the most commonly upregulated genes in cancerous tissues, regardless of cancer type and tumor origin." (PMID 27385217, 2016). "In addition, the knockdown of FNDC3B decreased anchorage independent growth (AIG) and tumor formation in xenograft models." (PMID 27385217, 2016). "FNDC3B has roles in bone and tumor development, but no documented functions in the ovary." (PMID 40554460, 2025).
cancer (39 papers, 2013 to 2026). A tumor composed of atypical neoplastic, often pleomorphic cells that invade other tissues. "Dysregulation of FNDC3B is implicated in cancer progression through the promotion of epithelial-mesenchymal transition (EMT), metastasis, and modulation of multiple oncogenic signaling pathways." (PMID 41704736, 2026). "The results indicated that FNDC3B served as a reliable biomarker associated with immune infiltration in most cancers, exhibiting a positive correlation with intratumoral infiltration of B cells, CD8 + T cells, neutrophils, macrophages, and DCs." (PMID 38581008, 2024). "Clinical analysis of cancer patients' disease‐free survival has indicated that overexpression of FNDC3B is associated with recurrence and metastasis in various cancer types." (PMID 38403291, 2024). "In this study, we integrated data from the National Center for Biotechnology Information, the Cancer Genome Atlas, Genotype-Tissue Expression database, and Gene Expression Omnibus datasets to analyze FNDC3B expression and its association with various clinicopathological parameters." (PMID 38581008, 2024). "Four proteins (KRT14, Hornerin [HRNR], Cell Division Cycle Associated 8 [CDCA8], and Fibronectin Type III Domain Containing 3B [FNDC3B]) were identified as unique to all patient HGSC cells at the cancer–mesothelial interface following this high-stringency approach." (PMID 31443478, 2019). "Several studies have reported that the aberrant expression of FNDC3B has been observed in various cancers, acting as a potential biomarker, as well as in the brain tissue of patients with epilepsy and brain tumors." (PMID 41574767, 2026). "In cancer research, increasing attention has recently been directed toward the roles of circular (circ) RNAs derived from FNDC3B." (PMID 41574767, 2026). "Initially, we analyzed the correlation between FNDC3B expression and immune infiltration in pan-cancer." (PMID 38581008, 2024). "Firstly, we evaluated the expression of FNDC3B in normal tissues and in pan-cancer using data extracted from NCBI, TCGA and GTEx database, respectively." (PMID 38581008, 2024). "Fibronectin type III domain containing 3B (FNDC3B) is a transmembrane endoplasmic reticulum protein that has been shown to affect the progression of cancer." (PMID 38341592, 2024). "GBM exhibited a significantly higher cancer-to-normal ratio compared to other organs, and patients with high FNDC3B expression had a poor prognosis (p < 0.01)." (PMID 38137388, 2023). "Recently, FNDC3B has been reported to be highly expressed in various cancers, including GBM, and to have an oncogenic effect based on TCGA and GEO databases." (PMID 38137388, 2023). "In an investigation of FNDC3B expression in normal and cancer tissues from patients, the Oncopression database was utilized to analyze the cancer-to-normal ratio of FNDC3B in a total of 23,982 samples across various organs." (PMID 38137388, 2023). "We found that FNDC3B expression in LGG was ranked first among 21 different cancer types based on the FDR correction." (PMID 36275754, 2022). "Then, we evaluated the differentially expressed level of FNDC3B in TCGA pan-cancer data using GEPIA2." (PMID 36275754, 2022). "FNDC3B expression was positively correlated with TILs in several human cancer types, especially in LGG." (PMID 36275754, 2022). "Multiple members, including FNDC1, FNDC3A, and FNDC3B, demonstrated significant expression changes between cancer and surrounding normal tissue groups in the malignancies studied in this study." (PMID 36626432, 2022). "To examine the function of FNDC3B on OS in various cancers, we used OncoLnc online tool to perform Cox regression analysis." (PMID 36275754, 2022). "We first assessed the expression of FNDC3B in different tumors and normal tissues of multiple cancer types using the Oncomine database." (PMID 36275754, 2022).